KRT35 (keratin 35)
Synonyms: K35; HHA5; KRTHA5; Ha-5; HA5
Tractability: PROTAC: its protein half-life has been measured.
Gene: Protein-coding gene on chromosome 17 (41,476,710 to 41,481,151, reverse strand). Ensembl gene ENSG00000197079.
Subcellular location (Human Protein Atlas): Intermediate filaments
Pathways (Reactome):
Developmental Biology: Formation of the cornified envelope; Keratinization
Gene Ontology:
Molecular function: protein binding; structural constituent of skin epidermis; structural molecule activity
Biological process: anatomical structure morphogenesis; epithelial cell differentiation; intermediate filament organization; morphogenesis of an epithelium
Cellular component: extracellular exosome; extracellular region; cytoskeleton; cytosol; keratin filament
Genetic constraint (gnomAD): Loss-of-function variants: 35 observed, 46.32 expected, observed/expected ratio (o/e) 0.76, 90% interval 0.58 to 1. The upper end of that interval is the gene's LOEUF score, 1, which puts it in group 4 of 6, group 1 being the genes least tolerant of losing a copy. Missense variants: 579 observed, 608.91 expected, observed/expected ratio (o/e) 0.95, 90% interval 0.89 to 1.02. Synonymous variants: 216 observed, 247.58 expected, observed/expected ratio (o/e) 0.87, 90% interval 0.78 to 0.98.
Homologues: Orthologues: chimpanzee KRT35 (99% identical), macaque KRT35 (96% identical), mouse Krt35 (91% identical), dog KRT35 (91% identical), rat Krt35 (91% identical), rabbit KRT35 (89% identical), pig KRT35 (89% identical), guinea pig KRT35 (84% identical). Paralogues in human: KRT36 (69% identical), KRT32 (66% identical), KRT31 (63% identical), KRT33A (62% identical), KRT33B (61% identical), KRT34 (60% identical), KRT40 (57% identical), KRT38 (55% identical), KRT39 (54% identical), KRT37 (53% identical), KRT14 (47% identical), KRT17 (47% identical), and 56 more.
Diseases named in the same sentence as KRT35 in open-access papers:
KRT35 is named in the same sentence as 5 diseases in open-access papers, as found by Europe PMC text mining. Sharing a sentence is not in itself a finding about the gene and the disease.
KRT35 shares sentences with these, for which no sentence is quoted: influenza (2 papers); cardiovascular diseases (1); infection (1); iron deficiency (1); neurodegenerative disease (1).